MED14 (mediator complex subunit 14)
Description:
Component of the Mediator complex, a coactivator involved in the regulated transcription of nearly all RNA polymerase II-dependent genes. Mediator functions as a bridge to convey information from gene-specific regulatory proteins to the basal RNA polymerase II transcription machinery. Mediator is recruited to promoters by direct interactions with regulatory proteins and serves as a scaffold for the assembly of a functional preinitiation complex with RNA polymerase II and the general transcription factors.
Synonyms: Trap170; DRIP150; CRSP2; CXorf4; EXLM1; RGR1; CRSP150; CSRP
Tractability: Small molecule: a structure with a bound ligand is known. PROTAC: ubiquitination databases record sites on it; its protein half-life has been measured.
Gene: Protein-coding gene on chromosome X (40,648,305 to 40,735,877, reverse strand). Ensembl gene ENSG00000180182.
Subcellular location: Nucleus
Subcellular location (Human Protein Atlas): Nucleoplasm; Nuclear bodies; Vesicles
Pathways (Reactome):
Gene expression (Transcription): Generic Transcription Pathway; MLL4 and MLL3 complexes regulate expression of PPARG target genes in adipogenesis and hepatic steatosis
Developmental Biology: Transcriptional regulation of white adipocyte differentiation
Disease: RSV-host interactions
Metabolism: PPARA activates gene expression
Gene Ontology:
Molecular function: protein binding; transcription coactivator activity; transcription coregulator activity; nuclear vitamin D receptor binding
Biological process: positive regulation of DNA-templated transcription; positive regulation of transcription by RNA polymerase II; positive regulation of transcription initiation by RNA polymerase II; positive regulation of transcription elongation by RNA polymerase II; regulation of transcription by RNA polymerase II; RNA polymerase II preinitiation complex assembly
Cellular component: core mediator complex; mediator complex; membrane; nucleus; nucleoplasm
Homologues: Orthologues: chimpanzee MED14 (100% identical), macaque MED14 (99% identical), dog MED14 (99% identical), pig MED14 (99% identical), guinea pig MED14 (98% identical), rat Med14 (97% identical), mouse Med14 (97% identical), rabbit MED14 (90% identical), rat LOC103694537 (87% identical), tropical clawed frog med14 (82% identical), zebrafish med14 (79% identical), Drosophila melanogaster MED14 (41% identical), and 1 more.
Diseases named in the same sentence as MED14 in open-access papers:
MED14 is named in the same sentence as 21 diseases in open-access papers, as found by Europe PMC text mining. Sharing a sentence is not in itself a finding about the gene and the disease. The quoted sentences say what the papers report.
breast carcinoma (3 papers, 2019 to 2023). "This pattern of dependence was similar to that observed for many light genes, including CRNKL1 in breast cancer cell lines and MED14 in leukaemia cell lines." (PMID 38117798, 2023). "MED1 and MED4 expression was generally slightly reduced with breast cancer progression, while MED14 expression was generally increased." (PMID 31695025, 2019). "In breast cancer, MED1 and MED4 expression was significantly reduced in tumors, while MED14 was increased." (PMID 31695025, 2019).
lymphoma (3 papers, 2016 to 2025). A malignant (clonal) proliferation of B- lymphocytes or T- lymphocytes which involves the lymph nodes, bone marrow and/or extranodal sites. "Notably, dysregulation of the mediator complex has been implicated in multiple cancer types, and human Med14 has been specifically found to be downregulated in lymphoma." (PMID 40571846, 2025). "Importantly, dysregulation of the mediator complex has been implicated in multiple cancer types, and human Med14 has been specifically found to be downregulated in lymphoma." (PMID 39553989, 2024). "Lymphoma was found as the only tumor entity to solely show underexpression of its Mediator subunits (most strongly MED28, MED14, MED13, CDK19, all with a frequency of 100%, n = 11/11)." (PMID 27050271, 2016).
bile duct carcinoma (1 paper, 2025). "Similarly, in humans, Mediator subunits MED12, MED14, MED23, and MED24 interact with YAP in bile duct carcinoma cells." (PMID 39752503, 2025).
chronic myeloid leukemia (1 paper, 2024). "Our study showed that the target genes of circ-Med14 were part of the MAPK and apelin signaling pathways, in addition to the progression of insulin resistance, hypertrophic cardiomyopathy, and chronic myeloid leukemia (CML)." (PMID 38967046, 2024).
diabetes (1 paper, 2025). "Phosphorylation of Med14 by PKA is essential for maintenance of enhancers that drive induction of beta cell-specific and diabetes-linked genes." (PMID 40667025, 2025).
melanoma (1 paper, 2019). A malignant, usually aggressive tumor composed of atypical, neoplastic melanocytes. "In melanoma, MED1 and MED14 was increased, while MED4 was reduced." (PMID 31695025, 2019).
Obesity (1 paper, 2025). Accumulation of substantial excess body fat. "Functional loss of MED14 not only inhibits pre-adipocyte differentiation but also improves insulin resistance and dyslipidemia in animal models, providing a new strategy for obesity treatment." (PMID 40940746, 2025). "Meanwhile, MED14 functions in regulating adipocyte differentiation and mitigates obesity." (PMID 40940746, 2025).
prostate carcinoma (1 paper, 2019). A carcinoma that arises from epithelial cells of the prostate gland. "Treatment of prostate cancer cells with enzalutamide enhances recruitment of pioneer factor GATA2, AR, Mediator subunits MED1 and MED14, and RNA Pol II to regulatory elements of enzalutamide-responsive genes." (PMID 31501863, 2019). "Our results suggest that GATA2 directs enzalutamide-induced transcription by recruiting AR, MED1/MED14, and Pol II to regulatory elements of enzalutamide-responsive genes, revealing a novel role of GATA2 in directing antagonist-mediated transcription in prostate cancer." (PMID 31501863, 2019).
cancer (6 papers, 2019 to 2025). A tumor composed of atypical neoplastic, often pleomorphic cells that invade other tissues. "An important implication of our results is that reduced levels of MED1, MED4, or MED14 may support specific cancer-associated alterations (e.g., SSX2 expression)." (PMID 31695025, 2019). "Together, these findings link MED14-centered Mediator function to endocrine and metabolic homeostasis and highlight how disruption of these interactions may contribute to metabolic disorders, endocrine dysfunction, and cancer." (PMID 41110510, 2025). "Of note, USP9X (log2FC/FDR = −0.31/1.7e-06), a previously reported cancer driver, TXLNG (−0.54/3.3e-17), OFD1, MED14, and CDK16 are known to evade X-inactivation and were over-expressed in females’ GC." (PMID 32849808, 2020).
tumor (5 papers, 2015 to 2025). "In vivo, Med1, Med14, Med21, and Cdk8 have been shown to be required in hair follicle stem cells, plant meristem, mouse blastocysts, and tumor cells, respectively." (PMID 25772472, 2015). "Among them, only three genes—MED6, MED14, and MED20—were found to be highly expressed in LUAD and essential for tumor cell growth." (PMID 40302793, 2025). "In general, TCGA RNA-seq data showed that expression of MED1, MED4, and MED14 are not lost in tumors, but varies considerably between tumor specimens compared normal." (PMID 31695025, 2019).
infection (1 paper, 2025). The state of being infected such as from the introduction of a foreign agent such as serum, vaccine, antigenic substance or organism. "Notably, 12 of these TFs exhibited distinct phosphorylation patterns upon infection, including MED14, SIN3A, BCL6, cJUN, NFATC1, STAT3, RUNX3, GTF2F1, MED1, JUNB, TLE3, and FOSL2." (PMID 40368139, 2025).
MED14 also shares sentences with these, for which no sentence is quoted: colon carcinoma (2 papers); hypertrophic cardiomyopathy (1); Insulin resistance (1); ischemia (1); leukaemia (1); metabolic disorders (1); myocardial infarction (1); neuroblastoma (1); neurological disorders (1); rheumatoid arthritis (1).